LHX2 (LIM homeobox 2)
Diseases named in the same sentence as LHX2 in open-access papers (continued):
Sharing a sentence is not in itself a finding about the gene and the disease.
cancer (13 papers, 2015 to 2024). A tumor composed of atypical neoplastic, often pleomorphic cells that invade other tissues. "Although there are more and more evidence showing that LHX2 is frequently up-regulated in human cancers, the mechanisms underlying the increased expression of LHX2 are poorly understood." (PMID 26189214, 2015). "Besides its roles in physiological conditions, LHX2 upregulation has been implicated in several types of human cancer." (PMID 26189214, 2015). "In this study, we first analyzed the expression levels of LHX2 in many malignancies by conducting a pan-cancer analysis." (PMID 37345110, 2023). "With the Wilcoxon rank sum test, we first utilized pan-cancer analyses to demonstrate LHX2 mRNA expression in different tumors." (PMID 37345110, 2023). "The Kaplan–Meier survival analysis of Pan-cancer showed that patients with high LHX2 expression had a shorter overall survival and disease-free survival when compared with patients with low LHX2 expression." (PMID 36011368, 2022). "LHX2 adjusts USP18 expression in cancers with poor prognosis." (PMID 39664521, 2024). "In addition to the well-established roles of LHX2 in physiological conditions, LHX2 is involved in various human cancers." (PMID 26189214, 2015). "Given the facts that miR-1238 is frequently down-regulated not only in human cancer tissues, but also in human epithelia-derived cancer cells and our data that LHX2 is required for NSCLC cell proliferation, leading us consider the possibility that miR-1238 may inhibit NSCLC cell proliferation." (PMID 26189214, 2015). "We also provide a previously unrecognized view of the potential synergisms between RUNX3 and CDX2, LHX2 and TCF3 in promoting the transcription of genes involved in cancer stem cell regulation and metastasis." (PMID 38240752, 2024). "Consistently, TCGA datasets from other types of cancers further verified the positive correlation between FGF1 and LHX2 expression." (PMID 35864158, 2022). "To explore this, we first examined LHX2 expression in 4 NSCLC cell lines and 50 paired NSCLC tissues and adjacent cancer-free lung tissues." (PMID 26189214, 2015). "In human cancers, dysregulated expression of LIM-homeobox gene 2 (LHX2) and downregulation of miR-1238 has been reported separately." (PMID 26189214, 2015). "Among the top 100 gene elements on this axis, we selected 10 candidates, including RAB39A, CPVL, NUP210 and LHX2, which were robustly expressed in cancer cells and CSCs but not in normal MSCs or Fb in both acidic and neutral environments." (PMID 29515775, 2018). "Although the other five genes RPL32, TMEM59L, LOC642929, LHX2, and TLCD3B have not been identified in clinical studies indicating their effect on cancers, they may be considered candidate oncogenes because of their high ranking in our constructed gene network modules." (PMID 33708239, 2021).
neurodevelopmental disorder (2 papers, 2015 to 2023). A behavioral and cognitive disorder with onset during the developmental period that involves impaired or aberrant development of intellectual, motor, or social functions. "Until recently, LHX2 defects had not been linked to neurodevelopmental disorders, with the exception of a few variants described in a large study on developmental disorders and in an autism cohort." (PMID 38094004, 2023).
adenocarcinoma (1 paper, 2023). A common cancer characterized by the presence of malignant glandular cells. "The mRNA expression of LHX2 was greatly increased in BRCA, ACC, bladder urothelial carcinoma (BLCA), cervical squamous cell carcinoma and adenocarcinoma (CESC), and most other tumors, despite the opposite results appearing in a few types of tumors." (PMID 37345110, 2023).
LHX2 also shares sentences with these, for which no sentence is quoted: epilepsy (2 papers); head and neck squamous cell carcinoma (2); acute lymphoblastic leukemia (1); age-related macular degeneration (1); alcohol dependence (1); autism (1); bipolar disorder (1); Cirrhosis (1); clear cell renal cell carcinoma (1); colon adenocarcinoma (1); colorectal cancer (1); ependymoma (1); follicular lymphoma (1); glaucoma (1); glioma (1); kidney cancer (1); lipoma (1); liposarcoma (1); Lissencephaly (1); lung adenocarcinoma (1); myeloproliferative disorder (1); Nephroblastoma (1); ovarian carcinoma (1); pituitary hormone deficiency (1); retinitis pigmentosa (1); round cell liposarcoma (1); Sandhoff disease (1); T-cell leukemia (1); teratoma (1); uterine carcinosarcoma (1).